KIF7 (kinesin family member 7)
Description:
Essential for hedgehog signaling regulation: acts both as a negative and positive regulator of sonic hedgehog (Shh) and Indian hedgehog (Ihh) pathways, acting downstream of SMO, through both SUFU-dependent and -independent mechanisms. Involved in the regulation of microtubular dynamics. Required for proper organization of the ciliary tip and control of ciliary localization of SUFU-GLI2 complexes (By similarity). Required for localization of GLI3 to cilia in response to Shh. Negatively regulates Shh signaling by preventing inappropriate activation of the transcriptional activator GLI2 in the absence of ligand. Positively regulates Shh signaling by preventing the processing of the transcription factor GLI3 into its repressor form. In keratinocytes, promotes the dissociation of SUFU-GLI2 complexes, GLI2 nuclear translocation and Shh signaling activation (By similarity). Involved in the regulation of epidermal differentiation and chondrocyte development (By similarity).
Synonyms: JBTS12; ACLS; AGBK; HLS2; MMEDF; UNQ340
Tractability: Small molecule: a structure with a bound ligand is known. PROTAC: UniProt records ubiquitination sites on it; ubiquitination databases record sites on it.
Target class: Other cytosolic protein
Gene: Protein-coding gene on chromosome 15 (89,608,789 to 89,663,098, reverse strand). Ensembl gene ENSG00000166813.
Subcellular location: Cell projection, cilium; Cytoplasm, cytoskeleton, cilium basal body
Subcellular location (Human Protein Atlas): Primary cilium; Primary cilium tip; Cytosol; Nucleoli fibrillar center
Pathways (Reactome):
Signal Transduction: Hedgehog 'off' state; Hedgehog 'on' state
Gene Ontology:
Molecular function: microtubule motor activity; protein binding; ATP binding; microtubule binding
Biological process: negative regulation of smoothened signaling pathway; positive regulation of smoothened signaling pathway; microtubule-based movement
Cellular component: ciliary tip; cilium; ciliary basal body; kinesin complex
Genetic constraint (gnomAD): Loss-of-function variants: 104 observed, 117.91 expected, observed/expected ratio (o/e) 0.88, 90% interval 0.75 to 1.04. The synonymous counts are far from expectation, so gnomAD's model fits this gene poorly and the ratio says little. Missense variants: 1,956 observed, 1,688.8 expected, observed/expected ratio (o/e) 1.16, 90% interval 1.12 to 1.2. Synonymous variants: 867 observed, 725.95 expected, observed/expected ratio (o/e) 1.19, 90% interval 1.13 to 1.26.
Homologues: Orthologues: macaque KIF7 (97% identical), chimpanzee KIF7 (94% identical), dog KIF7 (90% identical), guinea pig KIF7 (89% identical), pig KIF7 (89% identical), mouse Kif7 (89% identical), rat Kif7 (89% identical), tropical clawed frog kif7 (62% identical), zebrafish kif7 (58% identical). Paralogues in human: KIF27 (41% identical), KIF21A (24% identical), KIF21B (24% identical), KIF4A (22% identical), KIF4B (22% identical), CENPE (22% identical), KIF15 (19% identical), KIF5A (19% identical), KIF13B (18% identical), KIF1B (18% identical), KIF5C (18% identical), KIF1A (18% identical), and 29 more.
Diseases named in the same sentence as KIF7 in open-access papers:
KIF7 is named in the same sentence as 74 diseases in open-access papers, as found by Europe PMC text mining. Sharing a sentence is not in itself a finding about the gene and the disease. The quoted sentences say what the papers report.
ciliopathy (20 papers, 2012 to 2025). A genetic disorder of the cellular cilia or the cilia anchoring structures, the basal bodies, or of ciliary function. "In a second family, an additional variant of uncertain significance was reported in KIF7, which is a ciliopathy gene associated with variable phenotypes (including Joubert-12) and is a strong candidate for disease modification." (PMID 40428346, 2025). "Since 2011, 10 studies have identified patients carrying mutations in the KIF7 gene responsible for ciliopathies classified according to clinical features as hydrolethalus, acrocallosal, Joubert, and Greig cephalopolysyndactyly syndromes." (PMID 40956303, 2025). "Further research showed that KIF7 mutations cause ciliopathies through dysregulation of the Hedgehog (HH) signaling pathway components and that KIF7 is a key mediator in the HH signaling pathway through the regulation of Gli transcription factor targets." (PMID 38646780, 2024). "Homozygous KIF7 mutations have also been reported in Joubert syndrome; a ciliopathy with phenotype overlapping with the ACL syndrome." (PMID 38646780, 2024). "Novel heterozygous missense mutations have also been identified in KIF7 and shown to be associated with primary cilia defects that lead to ciliopathies, in particular the Bardet-Biedl syndrome." (PMID 38646780, 2024). "Mutations in KIF7 are associated with the ciliopathy Joubert syndrome and especially acrocallosal syndrome, which both fit with the patient’s symptoms." (PMID 32040484, 2020). "Mutation or dysregulation of Cc2d2a, Tmem67, Kif7 plus Tmem107 and Topors, are known to cause ciliopathies." (PMID 30260431, 2018). "Among them, Tmem67, Cc2d2a and Kif7 mRNAs were linked to Joubert syndrome and Meckel Gruber syndrome, both belonging to the ciliopathy family." (PMID 30260431, 2018). "In vivo genetic interaction studies indicated that the knockdown of KIF7 could exacerbate the ciliopathy transcripts since KIF7 expression in cell lines causes defects in cilia formation and induces abnormal centrosome duplication." (PMID 39063141, 2024). "Interestingly, five of the potential interactors (PIBF1, CSPP1, OFD1, C2CD3, and KIF7) have been linked to a single ciliopathy, the Joubert syndrome, reinforcing the role of CCP6 activity in cilia regulation." (PMID 36674791, 2023). "Due to a broad range of phenotypes in patients with Kif7 mutations, it may be useful to identify a group of Kif7-related ciliopathies." (PMID 32916978, 2020). "Biallelic mutations in KIF7 (MIM# 611254) have unfrequently been reported in a clinically variable group of ciliopathies (hydrolethalus syndromes, HLS, MIM# 614120; acrocallosal syndrome, ACLS, and Joubert-12, JBTS12, MIM# 200990; Al-Gazali-Bakalinova syndrome, MIM# 607131)." (PMID 32164589, 2020). "The c.428delG (p.Arg143Lysfs*4) mutation was identified in heterozygous state in patient MD1, in trans to a nonsense mutation, and in a patient G2 who is also heterozygous for a KIF7 (JBTS12) frameshift mutation and variants in three other known ciliopathy genes." (PMID 26386247, 2015). "Besides KIAA0586, HYLS1 and KIF7 are also known for being causative of ciliopathies, indicating that all three genes may have similar or converging genomic pathways." (PMID 39063141, 2024). "In addition, KIF12 variants may modulate the severity of a broader spectrum of hepato-renal fibrocystic disorders or even trigger a ciliopathy such as KIF7 mutation-induced Joubert syndrome." (PMID 26295839, 2015). "There is emerging evidence that Kinesin family member 7 (Kif7) promotes Hedgehog (Hh) signaling during embryonic development, and its misregulation contributes to diseases such as ciliopathies and cancer." (PMID 26439735, 2015). "Some ciliopathies are caused by mutations in genes that are primarily associated with non-ciliopathy syndromes (for example, TRIM32/BBS11, NPHP3, and KIF7)." (PMID 23351659, 2012).
ciliopathy (continued). "The retina is not commonly affected by mutations in Kif7; however, it has been suggested to be a potential modifier of other ciliopathies." (PMID 28444310, 2017). "In summary, KIF7 is essential for the regulation of chondrocyte proliferation and differentiation, controls cilia length during ciliogenesis by promoting microtubule catastrophe, is a key mediator of HH signaling, and its deletion or disruption results in skeletal defects and ciliopathies." (PMID 38646780, 2024). "These genes are specifically associated with pathology in certain organs; for example, NPHP3 is associated with renal–hepatic–pancreatic dysplasia, BBS11/TRIM32 causes limb girdle muscular dystrophy, and KIF7 causes acrocallosal syndrome – none of these is considered a ciliopathy." (PMID 23351659, 2012). "Oligogenic inheritance or occurrence of genetic modifiers involving variation in a subset of ciliopathy-related genes (e.g. AHI1, CEP41, CC2D2A, TMEM67, KIAA0556 and KIF7) has been suggested to contribute to phenotype worsening." (PMID 32164589, 2020). "The four ciliopathy genes (BUBR1 [BUB1B], IFT80, KIF7 and TMEM216) we identified as modifiers of progenitor proliferation encode proteins localized to distinct ciliary compartments." (PMID 26206566, 2015).
acrocallosal syndrome (16 papers, 2012 to 2025). Acrocallosal syndrome (ACS) is a polymalformative syndrome characterized by agenesis of corpus callosum (CC), distal anomalies of limbs, minor craniofacial anomalies and intellectual deficit. "Acrocallosal Syndrome is an autosomal recessive disorder caused by variants in the kinesin family member 7 (KIF7) gene." (PMID 40370525, 2025). "The KIF7 gene exhibits variability in phenotypes and has been associated with Joubert syndrome, acrocallosal syndrome, and fetal hydrolethalus." (PMID 39036105, 2024). "Mutations in the KIF7 gene have been implicated in autosomal recessive conditions such as Joubert syndrome, acrocallosal syndrome, and fetal hydrolethalus, as well as in retinal degeneration and other ocular manifestations due to their effect on primary cilia." (PMID 39036105, 2024). "Acrocallosal syndrome is an autosomal recessive neurodevelopmental ciliopathy often caused by KIF7 mutations and phenotypically overlaps with Joubert syndrome." (PMID 32040484, 2020). "A homozygous variant in KIF7, associated with Acrocallosal syndrome/Joubert syndrome 12 (MIM # 200990) was excluded because it is classified as likely benign." (PMID 33076433, 2020). "Mutations in Kif7 cause Joubert syndrome and acrocallosal syndrome in man, and are embryonic lethal in mouse." (PMID 28444310, 2017). "Through genetic interaction, KIF7 gene has been recently shown to be causing Joubert syndrome and the spectrum of fetal hydrolethalus and acrocallosal syndromes." (PMID 22587682, 2012). "Kif7, a member of the kinesin 4 superfamily, is implicated in a variety of diseases including Joubert, hydrolethalus and acrocallosal syndromes." (PMID 22281744, 2012). "Acrocallosal syndrome (ACLS) results from nonsense or frameshift KIF7 mutations affecting the motor domain or the Gli binding site and presents with macrocephaly, mental retardation, polydactyly, hallux duplication, and characteristic facial features including hypertelorism and prominent forehead." (PMID 38646780, 2024). "Mutations in the KIF7 gene have been reported to cause Acrocallosal syndrome, which presents with a wide range of craniofacial abnormalities including macrocephaly, hypertelorism, short nose, broad nasal bridge, short philtrum with upturned upper lip, high and narrow palate." (PMID 25859222, 2015). "Our analysis resulted in the identification of a homozygous p.N1060S missense mutation in a highly conserved residue in KIF7, a regulator of Hedgehog signaling that has been recently found to be causing Joubert syndrome, fetal hydrolethalus and acrocallosal syndromes." (PMID 22587682, 2012). "Acrocallosal syndrome (ACLS) is a rare autosomal recessive syndrome with corpus callosum agenesis, facial dysmorphism, post-axial polydactyly of the hands and pre-axial polydactyly of the feet caused by KIF7." (PMID 40575596, 2025). "Putoux and co-workers (2012) reported on four compound heterozygotes who had an acrocallosal syndrome phenotype related to the KIF7 gene." (PMID 39036105, 2024). "Similarly, knockout mice for KIF7 died at birth, and a boy with acrocallosal syndrome (ACLS) who carries a novel homozygous KIF7 nonsense mutation had unilateral maldescensus testis." (PMID 35547823, 2022). "Recently, mutations in the Kif7 gene involved in ciliogenesis and GLI3 processing have been found in human patients suffering from acrocallosal syndrome, characterized by Corpus Callosum and digit malformations." (PMID 22479201, 2012).
Joubert syndrome (15 papers, 2012 to 2024). Joubert syndrome (JS) is characterized by congenital malformation of the brainstem and agenesis or hypoplasia of the cerebellar vermis leading to an abnormal respiratory pattern, nystagmus, hypotonia, ataxia, and delay in achieving motor milestones. "Our patient with a pathogenic heterozygous KIF7 mutation does not have neurological abnormalities or sclerodactyly associated with Joubert syndrome, but has hypertelorism and RP, probably due to the variable expressivity of KIF7 on the primary cilia." (PMID 39036105, 2024). "Joubert syndrome has been associated with more than 40 gene mutations, including KIF7 gene mutations." (PMID 39036105, 2024). "KIF7 mutations were identified in Acrocallosal and Joubert Syndromes and Kif7 plays critical roles in regulating Sonic hedgehog signaling by organizing the ciliary tip compartment." (PMID 33604340, 2021). "The KIF7 variant has previously been reported as pathogenic in an individual with Joubert syndrome (MIM 213300)." (PMID 32040484, 2020). "Mutation in the KIF7 locus has been linked to Joubert syndrome which is a rare, inherited developmental disorder characterized by cerebellar hypoplasia, ataxia, psychomotor delay, and an altered respiratory pattern in the neonatal period." (PMID 25265279, 2014). "This contrasts with the peri-natal lethality of mice homozygous for kif7 loss of function alleles, but mirrors the finding that some Joubert syndrome patients are homozygous for mutated KIF7 alleles that cause severe truncation of the protein." (PMID 24339784, 2013). "Kif7 mutations or dysregulation was found in diseases such as Joubert syndrome." (PMID 25265279, 2014). "This stands in contrast to the peri-natal lethality caused by loss of function alleles of kif7 in the mouse but interestingly, mirrors the finding that some Acrocallosal and Joubert syndrome patients are homozygous for loss of function alleles of the human KIF7 gene." (PMID 24339784, 2013). "Intriguingly, five of the candidate interactors found in our BioID-based interactomic study (i.e., C2CD3, PIBF1, CSPP1, OFD1, and KIF7) are related to a single rare pathology, the Joubert syndrome." (PMID 36674791, 2023). "Remarkably, zebrafish lacking all Kif7 function are viable, in contrast to the peri-natal lethality of mouse kif7 mutants but similar to some Acrocallosal or Joubert syndrome patients who are homozygous for loss of function KIF7 alleles." (PMID 24339784, 2013).
basal cell carcinoma (6 papers, 2017 to 2025). A carcinoma involving the basal cells. "In embryonic keratinocytes, inactivation of both Kif7 and Sufu, an additional regulator of Gli transcription factors, leads to a loss of epidermal differentiation and follicular fate, while in the adult this loss leads to the induction of basal cell carcinoma." (PMID 37239418, 2023). "Studies have shown that low KIF7 expression is associated with poor prognosis in epithelial ovarian cancer, and KIF7 has also been reported to inhibit basal cell carcinoma." (PMID 40295497, 2025). "Due to the role of Shh signaling in the pathogenesis of basal cell carcinoma of the skin, the role of Kif7 has been studied in keratinocytes." (PMID 37239418, 2023). "There is evidence of both Ptc and Kif7 (the human homolog of Cos2) being down-regulated in different human cancers, including basal cell carcinoma and ovarian cancer." (PMID 35468034, 2022). "Interestingly, numerous gene members in the basal cell carcinoma pathway were found to be regulated by multiple miRNAs, with the exception of POLK and KIF7; meanwhile, for many KmiRNAs, one of them (e.g., hsa-miR-320b, hsa-miR-18a-3p, and hsa-miR-370-3p) targets more than one gene members." (PMID 34395634, 2021).
breast carcinoma (4 papers, 2019 to 2021). "In addition to participating in the Hedgehog signaling pathway, KIF7 was also found to correlate with worse outcomes of breast cancer." (PMID 34840571, 2021).
hydrolethalus syndrome (4 papers, 2020 to 2024). Hydrolethalus (HLS) is a severe fetal malformation syndrome characterized by craniofacial dysmorphic features, central nervous system, cardiac, respiratory tract and limb abnormalities. "Hydrolethalus syndrome 2 (HLS2, OMIM 614120) has similar features to HLS1, but the causative variant resides in the KIF7 gene." (PMID 34831381, 2021). "These include Pallister‐Hall syndrome (PHS), as well as HPE9 and Culler‐Jones syndrome (CJS), due to dominant mutations in the GLI3 and GLI2 genes, respectively, and hydrolethalus syndrome related to recessive mutations in HYLS1 and KIF7." (PMID 31840946, 2020).
Intellectual disability (4 papers, 2020 to 2024). "Monoallelic variants in KIF7 have been linked to various congenital phenotypes that overlap with the features of Case 6 (cryptorchidism, scoliosis, epilepsy, DD/intellectual disability, characteristic facial features, etc.)." (PMID 38654924, 2024). "Interestingly, a follow-up study showed persistent severe intellectual disability in Kif7-mutated patients, while C5orf42-mutated patients showed improvement from severe to mild intellectual disability." (PMID 32916978, 2020).
lung carcinoma (3 papers, 2020 to 2022). "An additional effect of E6, but not of E7, is to inhibit the antitumor activity of LKB1, a serine-threonine protein kinase, in lung cancer cells by downregulating the expression of kinesin family member 7 (KIF7)." (PMID 36552201, 2022). "Our findings provide new evidence to support the important role of KIF7 in the pathogenesis of lung cancer and suggests new therapeutic targets." (PMID 32945133, 2020). "Our findings provide new evidence to support the important role of KIF7 in the pathogenesis of lung cancer and suggest new therapeutic targets." (PMID 32945133, 2020). "The expression of KIF7 was screened in the normal bronchial epithelial cell line HBE and lung cancer lines H1299, H460, and A549, respectively." (PMID 32945133, 2020). "For the first time in this study, we found that HPV16‐E6 but not E7 inhibited the antitumor activity of LKB1 in lung cancer cells by downregulating the expression of KIF7." (PMID 32945133, 2020). "Here, we demonstrated for the first time that E6 but not E7 inhibits the antitumor activity of LKB1 in lung cancer cells by downregulating the expression of KIF7." (PMID 32945133, 2020).
scoliosis (3 papers, 2021 to 2024). A congenital or acquired spinal deformity characterized by lateral curvature of the spine. "A variant in the ciliary kinesin KIF7 was found within one AIS family and specific KIF7 mutations produced scoliosis in zebrafish." (PMID 34208743, 2021).
B-cell lymphoma (2 papers, 2024 to 2025). "SUFU can be hydroxylated by the complex of P4HA2 and KIF7, which inhibits its function and amplifies Hh signaling in B-cell lymphoma." (PMID 40170839, 2025). "In conclusion, our study uncovers a novel regulatory axis involving P4HA2, KIF7, and SUFU in the Hh signaling pathway, shedding light on the intricate mechanisms governing B-cell lymphoma tumorigenesis." (PMID 38909089, 2024).
Bardet-Biedl syndrome (2 papers, 2012 to 2016). A ciliopathy with multisystem involvement. "Sequencing analysis of the KIF7 gene in six OFD VI patients revealed only one heterozygous missense mutation, which was also detected in two patients with Bardet-Biedl syndrome (each one also carrying another heterozygous mutation in a BBS gene), as well as in 3 out of 384 controls." (PMID 22236771, 2012).